SMYD2 (SET and MYND domain containing 2)
Diseases named in the same sentence as SMYD2 in open-access papers (continued):
Sharing a sentence is not in itself a finding about the gene and the disease.
glioma (5 papers, 2021 to 2024). A benign or malignant brain and spinal cord tumor that arises from glial cells (astrocytes, oligodendrocytes, ependymal cells). "Not only did they find that increased SMYD2 content led to increased glioma progression and low survival probability but also inhibited glioma cell sensitivity to chemotherapy." (PMID 39765675, 2024). "A tumor tissue microarray, using samples from 441 patients with glioma, was used to measure the presence of SMYD2." (PMID 36838987, 2023). "To directly investigate the functional role of SMYD2, we infected U373 glioma cells with lentiviruses expressing either non‐targeting control (shNT) or two independent shRNAs targeting SMYD2 (SMYD2#1 and #2, respectively)." (PMID 33459509, 2021). "The outcome revealed a significantly prolonged survival time in the shSMYD2 group with serial bioluminescent imaging confirming that SMYD2 silencing attenuated the tumor forming ability and progression of xenografted glioma cells." (PMID 33459509, 2021). "Collectively these data indicate that SMYD2 is essential to glioma tumor cell proliferation in vitro and tumor formation in vivo." (PMID 33459509, 2021). "Together these data suggest that SMYD2 influences the resistance of glioma cells to TMZ with implications for the chemoradiotherapy of glioma." (PMID 33459509, 2021). "Assessment of the in vitro growth of the U373 glioma cells demonstrated that their proliferative capacity was attenuated after SMYD2 silencing in comparison to the shNT‐treated cells." (PMID 33459509, 2021). "However, further studies should be conducted to gain a deeper understanding of the role of SMYD2 in brain cancer, especially given SMYD2’s potential involvement in glioma and GBM therapy resistance." (PMID 39765675, 2024). "Regarding brain cancers, SMYD2 has been shown to correlate with poor prognosis for glioma and GBM." (PMID 39765675, 2024). "Lastly, we confirmed the oncogenic role of SMYD2 in glioma tumor cells in functional assays." (PMID 33459509, 2021). "On this basis, we chose to further explore the oncogenic role of SMYD2 in glioma." (PMID 33459509, 2021). "Therefore, downregulating SMYD2 may be a promising target for glioma and GBM treatment with the added benefit of enhancing chemotherapy and radiotherapy sensitivity." (PMID 39765675, 2024). "In addition, TUBA1C, SBF2-AS1, and SMYD2 have similar expression and prognostic impact in glioma." (PMID 38552216, 2024). "Interestingly, cisplatin treatment of AZ505-pretreated glioma cells caused a significant decrease in SMYD2 expression when compared to glioma cells that were not pretreated." (PMID 36838987, 2023). "Finally, given the importance of temozolomide (TMZ) in the therapeutic management of glioma following surgical resection, we investigated whether SMYD2 confers TMZ resistance to glioma." (PMID 33459509, 2021). "Among these genes, the inhibition of SMYD2 by treatment with LLY-507 and shRNA suppressed glioma cell growth, indicating the significant oncogenic role of SMYD253." (PMID 39482529, 2024). "In the treatment of gliomas, SMYD1-mediated degradation of SMYD2 played an important role in reversing resistance to chemotherapeutic agents." (PMID 36838987, 2023). "Glioma cells were treated with TMZ alone and in combination with shRNA and inhibitor approaches to target SMYD2." (PMID 33459509, 2021). "As independent confirmation of these data, experiments utilizing the SMYD2 inhibitor, LLY‐507, demonstrated that targeting SMYD2 was effective in inhibiting the proliferation of U373 glioma cells." (PMID 33459509, 2021). "Here we showed through shRNA silencing and inhibitor approaches that SMYD2 is essential for cell proliferation, tumor formation, and TMZ resistance in glioma tumor cells." (PMID 33459509, 2021). "Additionally, SMYD2 silencing decreased the expression of other genetic regulators in an identified 13 gene-set, demonstrating that SYMD2 expression contributes to other elements involved in glioma formation." (PMID 39765675, 2024).
non-small cell lung carcinoma (5 papers, 2019 to 2023). A group of at least three distinct histological types of lung cancer, including non-small cell squamous cell carcinoma, adenocarcinoma, and large cell carcinoma. "Signaling pathway regulation studies showed that Baicalein also inhibited the SMYD2/RPS7 signaling pathway in human non-small-cell lung cancer cells." (PMID 35432530, 2022). "In conclusion, SMYD2 knockdown can inhibit the proliferation and invasion of human non-small-cell lung cancer A549 and NCI-H1299 cells." (PMID 35432530, 2022). "As a therapeutic target in non-small cell lung cancer (NSCLC), reducing SMYD2 activity via specific inhibitors appears to enhance the cell sensitivity to cisplatin but not to paclitaxel, vinorelbine, or vincristine sulfate." (PMID 36838987, 2023). "In non-small-cell lung cancer cells with emL4-ALK gene fusion, inhibition of SMYD2 expression or protein catalytic function leads to decreased levels of methylation and phosphorylation of EML4-AlK protein K1610, which inhibits cell growth." (PMID 35432530, 2022). "Multiple nonhistone proteins are methylated by SMYD2 to achieve these effects on tumors, for example, MAPKAPK3 in PDAC and ALK in non-small-cell lung cancer (NSCLC)." (PMID 31370883, 2019).
ovarian clear cell cancer (5 papers, 2021 to 2025). An invasive malignant neoplasm that arises from the ovary and is characterized by a predominance of clear and hobnail malignant epithelial cells. "Another histone modifier, SMYD2 (SET and MYND domain containing 2), a histone methyltransferase, enhances cell vitality in clear cell ovarian carcinoma through ER methylation, whereas inhibiting SMYD2 induces apoptosis in these cancer cells." (PMID 40290121, 2025). "The growth of cell lines with ovarian clear cell carcinoma is inhibited by SMYD2 suppression." (PMID 37513898, 2023). "SMYD2, a histone lysine methyltransferase that methylates H3K4 or H3K36, was significantly upregulated in ovarian clear cell carcinoma specimens compared with normal ovarian tissues." (PMID 34544413, 2021).
triple-negative breast carcinoma (5 papers, 2018 to 2024). An invasive breast carcinoma which is negative for expression of estrogen receptor (ER), progesterone receptor (PR), and human epidermal growth factor receptor 2 (HER2). "Overexpression of the gene for SMYD2 is linked to pathogenesis in adolescent B cell ALL (B-ALL) related to the MLL-AF9 oncogene and in triple-negative breast cancer with a poor patient prognosis." (PMID 36838987, 2023). "Silencing of SMYD2 by RNAi in triple-negative breast cancer (TNBC) cell lines or inhibition of SMYD2 with its specific inhibitor, AZ505, significantly reduced tumor growth in vivo." (PMID 29487338, 2018).
esophageal cancer (4 papers, 2018 to 2023). A primary or metastatic malignant neoplasm involving the esophagus. "Concerning histone methyltransferase enzymes, KMT3C/SMYD2 mRNA and protein were overexpressed in some oesophageal cancer cell lines compared to normal oesophagus." (PMID 32429269, 2020). "We hence measured the ability of these compounds to affect the growth of the esophageal cancer cell line KYSE-150, a SMYD2 over-expressing cell line previously reported to require SMYD2 activity for proliferation." (PMID 29856759, 2018).
abdominal aortic aneurysm (3 papers, 2018 to 2022). Enlargement and ballooning of the vessel that supplies arterial blood to the abdomen, pelvis and legs. "Furthermore, the methylation status of the Smyd2 promoter causes Smyd2 expression to be greatly downregulated in abdominal aortic aneurysm (AAA), according to genome-wide association studies (GWAS)." (PMID 36270984, 2022). "Recurrent data have demonstrated that Smyd2 plays a key role in several types of cancer, immune-inflammatory diseases, and abdominal aortic aneurysm." (PMID 36270984, 2022).
chronic lymphocytic leukemia (3 papers, 2016 to 2021). "Hence, SMDY2 could maintain mature B cells survival through the non‐canonical NF‐κB pathway and which could also explain why B cells are excessive activation in some autoimmune diseases and chronic lymphocytic leukemia accompanied by the high expression of SMYD2." (PMID 34841684, 2021).
diabetic nephropathy (3 papers, 2022 to 2024). "Importantly, the protein levels of SMYD2 were reduced in diabetic nephropathy (DN) mice after Ranunculus ternatus Thunb (Ranunculaceae, RTT) extract treatment, suggesting that Smyd2 may play a role in metabolic diseases." (PMID 36270984, 2022).
lymphoma (3 papers, 2016 to 2023). A malignant (clonal) proliferation of B- lymphocytes or T- lymphocytes which involves the lymph nodes, bone marrow and/or extranodal sites. "The data analysis demonstrated that higher expression of SMYD2 is present in a variety of human cancers, like breast, bladder, colorectal, cervical, esophageal, lymphoma, ovarian, head and neck, and pancreatic cancer." (PMID 37971632, 2023). "The maximum alterations (> 10%) for SMYD2 were observed in lymphoid cancer." (PMID 37971632, 2023). "Maximum alteration frequency of SMYD2 (> 10%) seems in lymphoid cancer patients." (PMID 37971632, 2023). "Finally, germ-line deleted Eμ-myc Smyd2−/− animals and Eμ-myc Smyd2+/+ controls showed comparable lymphoma onset." (PMID 27655694, 2016). "In our previous RNA profiling datasets, Smyd2 classified as a Myc-dependent serum response (MDSR) gene in mouse fibroblasts and was induced during lymphoma development in Eμ-myc mice, the latter validated here by RT-PCR." (PMID 27655694, 2016). "The absence of Smyd2 in lymphomas arising with CD19-CRE was confirmed at the mRNA level: it is noteworthy here that lymphomas are generally monoclonal, explaining the full loss of Smyd2, while mixed pre-tumoral populations still showed residual expression." (PMID 27655694, 2016).
ovarian carcinoma (3 papers, 2015 to 2024). A malignant neoplasm originating from the surface ovarian epithelium. "The SMYD2 gene mutations were searched in 4617 cancer samples from 11 different pan-cancer studies, including breast, cervical, bladder, colon, esophageal, kidney, head and neck, liver, lymphoid, pancreatic, and ovarian cancer." (PMID 37971632, 2023). "Additionally, using RNA-seq data analysis of early-stage (I and II) ovarian carcinoma patients, 29 histotype-specific biomarkers, including SMYD2, were discovered." (PMID 39482529, 2024). "However, using a DNA copy number threshold of 3 and above, SMYD2 is potentially amplified in 5–8% cases of breast, liver, melanoma, or ovarian cancer (right)." (PMID 25825497, 2015). "In ovarian cancer cell lines, increased sub-G1 and cleaved poly(ADP‒ribose) polymerase (PARP) levels were observed after treatment with SMYD2 siRNA and LLY-507, and a synergistic effect with PARP inhibitors was observed, confirming the utility of SMYD2 inhibitors in ovarian cancer." (PMID 39482529, 2024).
pancreatic ductal adenocarcinoma (3 papers, 2021 to 2024). An infiltrating adenocarcinoma that arises from the epithelial cells of the pancreas. "In pancreatic ductal adenocarcinoma, SMYD2 promotes tumor formation by promoting the methylation of Lys355 of human mitogen-activated protein kinase activated protein kinase 3 (MAPKAPK3)." (PMID 34335697, 2021). "SMYD2 promotes lysine methylation of MAPKAPK3 at site 355 in pancreatic ductal adenocarcinoma." (PMID 35432530, 2022).
renal carcinoma (3 papers, 2019 to 2023). A carcinoma arising from the epithelium of the renal parenchyma or the renal pelvis. "The effects of SMYD2 and SMYD2-mediated miRNAs on renal cancer cell proliferation, migration, clonogenicity, and tumorigenicity were determined via cell-function assays and murine xenograft experiments." (PMID 36838987, 2023). "Double immunofluorescent staining revealed the co-localization of the SMYD2 and P-gP proteins in renal cancer tissues." (PMID 31754403, 2019). "MicroRNA (miRNA)-microarray profiling identified differentially expressed miRNAs in renal cancer cells subjected to SMYD2 knockdown or treatment with the SMYD2 inhibitor AZ505." (PMID 31754403, 2019). "The estimated IC50 values of cisplatin, doxorubicin, or 5-FU (but not docetaxel) for AZ505-treated RCC cells were significantly lower than those for the control cells, indicating that the SMYD2 inhibition enhanced the drug sensitivity in renal cancer cells." (PMID 31754403, 2019). "The effects of SMYD2 and candidate SMYD2-mediated miRNAs on renal cancer cell proliferation, migration, clonogenicity, and tumorigenicity were determined via cell-function assays and murine xenograft experiments." (PMID 31754403, 2019). "The results of the MTS and EdU assays demonstrated that the viability and proliferation of renal cancer cells decreased significantly after the inhibition of SMYD2 via AZ505 treatment or siSMYD2-mediated knockdown." (PMID 31754403, 2019). "Therefore, combining an SMYD2 inhibitor with a chemotherapeutic agent resulted in synergistic therapeutic effects against renal cancer in vivo." (PMID 31754403, 2019). "Meanwhile, we performed MTS assays to verify whether miR-125b could reverse the SMYD2 knockdown-mediated suppression of the proliferation of renal cancer cells; the results showed that miR-125b could not reverse this suppression." (PMID 31754403, 2019).
Renal cyst (3 papers, 2019 to 2022). A fluid filled sac in the kidney. "Utilizing Pkd1 knockout mice and the SMYD2 inhibitor, AZ505, we showed that SMYD2 is a critical mediator of renal cyst growth in ADPKD." (PMID 35847973, 2022). "By utilizing Pkd1-knockout mice and AZ505, a specific inhibitor of SMYD2, they demonstrated that SMYD2 is a critical mediator of renal cyst growth." (PMID 31866860, 2019).
squamous cell carcinoma (3 papers, 2019 to 2023). A carcinoma arising from squamous epithelial cells. "Approximately 60–70% of patients with human papillomavirus (HPV)-unrelated head and neck squamous cell carcinoma (HNSCC), another type of squamous cell carcinoma, have SMYD2 overexpression, and these patients have a worse overall survival rate than those with low SMYD2 expression." (PMID 31370883, 2019).
breast tumor (2 papers, 2015 to 2018). "∼28% of breast tumors show both SMYD2 amplification as well as higher gene expression compared with diploid samples." (PMID 25825497, 2015).
clear cell renal cell carcinoma (2 papers, 2019 to 2024). "This study aims to investigate SMYD2 as a prognostic indicator of clear cell renal cell carcinoma (ccRCC) and explore its role in tumorigenesis and multi-drug resistance." (PMID 31754403, 2019). "However, the regulatory mechanism of SMYD2 in the modulation of circRNA remains unclear, this provides a compelling impetus for further exploration of its function in the context of renal clear cell carcinoma." (PMID 39440063, 2024).
ischaemic stroke (2 papers, 2022 to 2024). "Thus, the upregulation of Smyd-2 in CIR may offer valuable insights into the molecular mechanisms underlying ischemic stroke pathogenesis." (PMID 39682718, 2024). "This study underscores Smyd-2’s potential for ischemic stroke treatment by disrupting the Smyd-2/Nrf-2-driven antioxidant capacity, leading to hippocampal neuronal ferroptosis." (PMID 39682718, 2024). "Given the constitutive expression of Smyd-2 in hippocampal neurons and its quick-acting Nrf-2-dependent curative pathway, the regimen of Smyd-2-related compounds will be viable clinically against ischemic stroke." (PMID 39682718, 2024). "Our findings highlight Smyd-2’s potential as a therapeutic target for ischemic stroke, advancing our understanding of ferroptosis and oxidative stress in neuronal injury." (PMID 39682718, 2024). "We performed loss‐of‐function and gain‐of‐function studies to investigate the biological function of Smyd2 in ischaemic stroke." (PMID 35297562, 2022). "In the present study, we addressed the important role of endothelial cell Smyd2 in Sphk/S1PR signalling during cerebral ischaemia and showed that Smyd2 controls endothelial permeability by regulating Sphk/ S1PR methylation in ischaemic stroke." (PMID 35297562, 2022). "Here, we show that Smyd2 is elevated after MCAO, especially in the brain endothelium, implying that Smyd2 might play a significant role in brain pathology during reperfusion following ischaemic stroke." (PMID 35297562, 2022). "Overall, these results reveal a novel role for Smyd2 in BBB disruption in ischaemic stroke, suggesting that Smyd2 may represent a new therapeutic target for ischaemic stroke." (PMID 35297562, 2022). "There is evidence that inflammatory processes are involved in brain damage after ischaemic stroke, and we found that the MCAO‐induced upregulation of inflammatory mediators were inhibited by Smyd2 knockdown." (PMID 35297562, 2022). "We explored the effects of Smyd2 knockdown on the expression of Claudin‐1/5 and ZO‐1 after MCAO and found that Smyd2 knockdown reversed the decrease in Claudin‐1/5 and ZO‐1 after ischaemic stroke." (PMID 35297562, 2022).
myocardial infarction (2 papers, 2010 to 2018). Gross necrosis of the myocardium, as a result of interruption of the blood supply to the area, as in coronary thrombosis. "In one study, protein levels of Smyd2 were decreased in cardiomyocytes after cellular apoptosis and after myocardial infarction." (PMID 29507647, 2018). "In addition, SMYD2 deletion in cardiomyocytes in vivo promoted apoptotic cell death upon myocardial infarction." (PMID 29507647, 2018).
steatosis (2 papers, 2023). Increased lipid within the cytoplasm of cells. "Surprisingly, knockout of Tbx3 (transcription factors) and Smyd2 (epigenetic factor) resulted in the most significant reduction of liver injury and steatosis, even though Tbx3 and Smyd2 have not been linked to NAFLD/NASH pathogenesis before." (PMID 37620333, 2023).
acute kidney injury (1 paper, 2022). Sudden and sustained deterioration of the kidney function characterized by decreased glomerular filtration rate, increased serum creatinine or oliguria. "Currently, the role of SMYD2 in acute kidney injury (AKI) remains unknown." (PMID 36046818, 2022).
age (1 paper, 2022). A temporal measurement of the time period elapsed since an identifiable point in the life cycle of an organism. "In light of this, we found Smyd2 knockdown or heterozygous knockout mice ameliorates endothelial inflammation (iNOS, VCAM-1 and COX-2) upon Ang II infusion in vivo, which revealed that targeting Smyd2 possibly unveiled a novel therapeutic candidate of age-related endothelial inflammation." (PMID 36585926, 2022).
aneurysm (1 paper, 2018). Bulging or ballooning in an area of an artery secondary to arterial wall weakening. "This demonstrates that transcript expression differences are also reflected from a translational perspective at the site of aneurysm, which is in turn associated with SMYD2 promoter methylation." (PMID 29507647, 2018).
Aortic dissection (1 paper, 2019). Aortic dissection refers to a tear in the intimal layer of the aorta causing a separation between the intima and the medial layers of the aorta. "A myeloid cell- or vascular smooth muscle cell (VSMC)-specific SMYD2 knockout mouse model is needed to ascertain the function of SMYD2 in AAA/aortic dissection and other cardiovascular diseases." (PMID 31370883, 2019). "However, the exact role and molecular mechanisms of SMYD2 in AAA or even aortic dissection remain unclear." (PMID 31370883, 2019).
Arthritis (1 paper, 2021). Inflammation of a joint. "The Smyd2+/‐ mice were much more retarded to collagen‐induced arthritis, however, the WT mice lost more body weights and exhibited markedly exacerbated inflammation effects (paw inflamed and swollen)." (PMID 34841684, 2021).